MMP3 (matrix metallopeptidase 3)
Diseases named in the same sentence as MMP3 in open-access papers (continued):
Sharing a sentence is not in itself a finding about the gene and the disease.
tumor (continued). "Since UBD stabilizes and increases MMP3 expression, the UBD–MMP3 axis may enhance ECM remodeling and create a lung microenvironment that favors tumor cell adhesion and survival." (PMID 41583390, 2026). "These analyses suggested that tumor cells might promote differentiation of CD34+ Fbs into APOE+ Fbs and MMP3+ Fbs in D‐TGCT, turning “mild” fibroblast clusters into “aggressive” ones." (PMID 40126353, 2025). "FGF-1 influences tumor progression through the phosphorylation of FGF-4, activation of the MAPK/ERK pathway, and increased expression of EMT-related genes such as Snail-1 and MMP3." (PMID 40136652, 2025). "Similarly, matrix metalloproteinases MMP1, MMP3 and MMP12 are crucial regulators of tumour angiogenesis, vascular structure, permeability and integrity." (PMID 39161078, 2025). "The authors proposed as a mechanism the altered lung microenvironment by the primary tumor through the local expression of vasopermeability factors, namely Angpt 2, MMP3, and MMP10, but not VEGF." (PMID 40435350, 2025). "This suggests that MMP3 knockdown affects tumor biology but is not sufficient on its own to shrink tumors within the study timeframe." (PMID 40362252, 2025). "Surprisingly, multiple injections of liposomal MMP3-siRNA increased, although not statistically significant, tumor weight in the siMMP3 group compared to the negative control (NC) group." (PMID 40362252, 2025). "While MMP3-siRNA monotherapy did not reduce tumor growth in vivo, its combination with cisplatin significantly inhibited tumor growth in a cisplatin-resistant HGSOC xenograft model." (PMID 40362252, 2025). "MMP1, MMP3, and MMP9 have also been shown to play critical roles in tumor metastasis." (PMID 40486048, 2025). "Similarly, MMP-1 and MMP-3 are engaged in promoting EMT, a process that facilitates tumorigenesis and accelerates the invasion of tumor cells." (PMID 40564842, 2025). "While liposomal MMP3-siRNA alone did not significantly reduce tumor size, it lowered cell proliferation and angiogenesis." (PMID 40362252, 2025). "The control of protein translation plays a key role in cancer development and progression because proteins synthesis is required to increase cancer cells' biomass for cell division, as well as to translate proteins involved in tumor growth and invasion (e.g., BCL‐xL, cyclins, MMP3, VEGF)." (PMID 39092562, 2024). "Interestingly, the elevated expression of MMP1, MMP2, and MMP3 observed in 3D CAF monocultures was downregulated in 3D co-cultures, indicating a tumor-mediated suppressive effect on these genes." (PMID 39700125, 2024). "Expression analysis showed that MMP3, MMP9, TIMP1 and VEGFA were upregulated in tumor samples." (PMID 39177661, 2024). "A small number of MMP13+ cells were localized to the front lines where infiltrating immune cells attacked tumor cells, but neither MMP3+ nor MMP9+ cells were localized." (PMID 38774209, 2024). "In HSCC, MMP3 expression may correlate with the activation and aggregation of CAF, impacting tumor progression and prognosis." (PMID 38720887, 2024). "MMP3, TIMP1, and TIMP2 play critical roles in tumor invasion." (PMID 38921985, 2024). "Tissue Factor Pathway Inhibitor 2 (TFPI‐2), a Kunitz‐type serine protease inhibitor, impedes the invasion and metastasis ability of tumour cells via inhibiting the activities of Matrix Metallopeptidase 1 (MMP1), Matrix Metallopeptidase 3 (MMP3), plasmin and trypsin." (PMID 39462685, 2024). "Additionally, a bioinformatic study mirrored our results by demonstrating MMP1, MMP3, and MMP12 up-regulation in CRC, highlighting the potential universal relevance of these MMPs in tumor progression." (PMID 39596132, 2024). "MMP3 is capable of degrading ECM, which facilitates tumor invasion and metastasis." (PMID 37940644, 2023). "The increased expression of MMP3 may also activate other MMPs, such as MMP1 and MMP9, which can promote tumor cell passage through the basement membrane and lead to invasion and metastasis." (PMID 36412203, 2023).
tumor (continued). "In addition, metalloproteinases MMP3, MMP9, MMP10 and MMP13, known to promote tumor growth, were upregulated by CX3CL1 mediated activation of CX3CR1." (PMID 37771579, 2023). "In addition, CAFs can remodel the ECM by degrading normal ECM components; secreting multiple matrix proteins; producing MMPs, including MMP-1 and MMP-3; increasing ECM stiffness; and facilitating tumor progression." (PMID 37726803, 2023). "Furthermore, CAFs secrete MMP-1, MMP-3, MMP-7, MMP-9, and MMP-13, releasing ECM-bound growth factors such as VEGF supporting tumor angiogenesis." (PMID 35572966, 2022). "Matrix metalloproteinase 3 (MMP3) is a protein involved in the degradation of components of the extracellular matrix (fibronectin, laminin, collagens III, IV, IX, and X, and cartilage proteoglycans), with a known role in tumour initiation." (PMID 36923728, 2022). "FN1, APOA1, CXCL8, MMP1, MMP3, and THBS1 were significantly upregulated in the tumor samples." (PMID 35719376, 2022). "Moreover, TNF is a proinflammatory cytokine secreted by macrophages, T-lymphocytes and mastocytes, inducing an overexpression of MMP-2, MMP-3, MMP-7 and MMP-9 in the tumor microenvironment, contributing to the invasive capacity of malignant cells." (PMID 34204372, 2021). "From this, they were able to induce matrix MMP3 and MMP13 expression specifically upon ligation of the CAR and its antigen to remodel tumor microenvironment, increase T cell infiltration, and reduce tumor growth in vivo." (PMID 33790906, 2021). "Therefore larger studies considering multiple factors, such as OSA grade and anatomical location, need to be undertaken and compared to non-tumor tissue, in order to contextualize the complex expression patterns of GLUT1, MMP3 and NRF2." (PMID 34414229, 2021). "The present study shows that there is a statistically significant association between the immunohistochemical expression of MMP-1 and MMP-3 in the breast tissue of women suffering BC and their expression in the tissue of patients without tumor disease." (PMID 34445715, 2021). "We identified differential mRNA expression of the solute carrier family 2 member 1 (SLC2A1/GLUT1), matrix metallopeptidase 3 (MMP3) and nuclear factor erythroid 2–related factor 2 (NFE2L2/NRF2) genes in canine OSA tissue in comparison to paired non-tumor tissue." (PMID 34414229, 2021). "In vitro study of GPNMB-expressing tumor cells showed no impact on cellular growth or death but increased expression of MMP-3 and MMP-9 as well as increased invasiveness." (PMID 34108545, 2021). "MMP-3 can degrade ECM, which is beneficial for tumor invasion and metastasis." (PMID 34276395, 2021). "Analysis with TIMER showed strong correlation between NRP1 expression and the abundance of tumor progression-related genes, MMP1, MMP3, MMP9, VEGFC, FLT4 and CXCL12 in LUSC, while there isn’t clear association between NRP1 expression and this panel of pro-tumorigenic genes in LUAD." (PMID 34168096, 2021). "Since MMP3 is known to be involved in tumor cell invasion, we investigated whether TNFα induces FDCLC migration and whether MMP3 expression is required for this." (PMID 34222497, 2021). "Other authors have shown the important roles of MMP-3 in tumor progression and overall survival; however, unlike our study, none of the other studies have measured the expression of four MMPs in the biopsies of cancer patients." (PMID 34445715, 2021). "It has been shown that some members of the family of MMPs promote tumor growth, angiogenesis, epithelial–mesenchymal transition (EMT), and premetastatic niche formation in cancer patients, as is the case with MMP-1, MMP-2, MMP-3, and MMP-9." (PMID 34445715, 2021).
tumor (continued). "MMP‐3 levels increased in patients with hormone‐positive tumours compared with those with hormone‐negative tumours, having an increase in both groups throughout the treatment with RT." (PMID 31568637, 2020). "Of them, MMPs, MMP2, MMP3 and MMP9 could induce tumor cell invasion and migration by promoting the degradation of extracellular matrix, such as collagen." (PMID 32924971, 2020). "Indeed, this MMP3 was found to be increased in EO771.LMB cells, isolated from a spontaneous lung metastasis from an EO771 tumour-bearing compared with parental EO771." (PMID 32699527, 2020). "MMP-3 as one of the most important MMPs has been correlated to metastases by promoting epithelial–mesenchymal transition (EMT), it is also capable of activating MMP-1, which increases the capacity of the tumor cells to invade." (PMID 33167431, 2020). "Respect to E‐cadherin, patients with E‐cadherin positive tumours also showed higher MMP‐3 levels than those with negative E‐cadherin, having a progressive increase in the E‐cadherin positive group throughout RT." (PMID 31568637, 2020). "The proteases MMP-3 and MMP-9 also contribute to tumor progression." (PMID 33352765, 2020). "Intriguingly, in many solid tumors, MMPs are produced by tumor stromal cells, rather than by tumor cells, including tumor-associated interstitial collagenase (MMP-1), stromelysin-1 (MMP-3), stromelysin-3 (MMP-11), and gelatinase A (MMP-2)." (PMID 32948029, 2020). "Indeed, we have shown that both MMP3 and MMP9 were expressed at high levels in LuM1 cells and proved their important roles in tumor progression." (PMID 32429403, 2020). "Expression for MMP3 (t = 4.884, p < 0.0001), SLC2A1 (t = 3.703, p = 0.0006), DDK3 (t = 3.981, p = 0.0003), POSTN (t = 2.061, p = 0.0455), RBP4 (t = 3.048, p = 0.004) and ASPN (t = 2.733, p = 0.0091) was confirmed to be higher in the tumor tissues." (PMID 32854182, 2020). "Thus, MMP3, CCN2/CTGF, and their EVs can be produced on both sides of the interaction to promote tumor–stroma malignant conversion." (PMID 32260433, 2020). "These cells establish a favorable environment for tumor development by releasing cytokines (IL-6, IL-10 and TGF-β), metalloproteinases (MMP3 and MMP9) and growth factors (HGF, EGF, CTGF and IGF-1), leading to immunomodulation, angiogenesis, invasion, proliferation and tumor cell survival." (PMID 32899449, 2020). "Little to no MMP3 was observed in the tumor of mice injected with MDA-MB-231GFP/Luc2 cells plus either EO-231 (~ 17% of cells) or MC3T3-E1 cells (~ 5% of cells)." (PMID 30813947, 2019). "For example, MMP-3 and MMP-7 interact in vivo with osteopontin at tumor sites and may be related to the angiogenic process during tumor development." (PMID 31921634, 2019). "Hence we validated gene expression of MMP1, MMP3, MMP11, MMP13, MMP14, ADAMTS1 and ADAMTS5 genes belonging to metallopeptidase activity, using qPCR in 67 tumours." (PMID 31292488, 2019). "TNFα‐CSG treatment did not affect protease gene expression in tumour CD11b+ cells or in cultured 4T1 tumour cells (with the exception of MMP3) (Fig EV4A)." (PMID 31709774, 2019). "Moreover, DGCR5 also lead to significant expression in migration and invasion‐related marker MMP‐3 and MMP‐9 in tumor samples." (PMID 29790668, 2018). "In obese tumor patients treated with amiloride, increased MMP3 protein levels and MMP9 activities were detected in tumor tissues, suggesting that exosome-mediated MMP3 protein transfer and subsequent MMP9 activation may also occur in the human body." (PMID 29137230, 2017). "MMP-3 was shown to promote EMT and was suggested to be a natural tumor promoting factor." (PMID 28398251, 2017). "MMP2, MMP3, MMP9, uPA and Cathepsin B play critical roles in tumor invasion and metastasis." (PMID 29137230, 2017). "Immunohistochemistry results revealed that MMP3 protein levels in lung tumor tissues from obese tumor patients were increased compared with non-obese tumor patients." (PMID 29137230, 2017).
tumor (continued). "Indeed, estrogen induces neutrophil expression of a plethora of genes encoding protumoral cytokines/chemokines(e.g. CXCL1, CXCL2, S100A8, S100A9), matrix metalloproteinases(MMP3, MMP9) and COX-2 that are all known to promote tumor growth and metastasis." (PMID 28429725, 2017). "However, although at lower transcriptional levels, MMP3 and 19 were significantly upregulated whereas MMP13 were significantly downregulated in the SG-/- primary tumour tissue." (PMID 27223472, 2016). "This is consistent with induction of MMP3 and MMP9 observed in eAGR2-treated non-tumor organoids." (PMID 27240165, 2016). "Thus, we observed expression of matrix metalloproteinases (MMP)-1, MMP-2, MMP-3, and MMP-9 mainly in the nuclei of tumor cells, while for MMP-3 and MMP-9 the immunoreactivity was also present in the cytoplasm of tumor cells and in the amyloid deposits." (PMID 27871286, 2016). "Although these data strongly support the notion that modulation of tumor-derived MMP3 expression levels affected tumor progression in a cell-intrinsic manner, this still does not necessarily exclude the possibility for extrinsic mechanisms." (PMID 26008967, 2015). "In addition to MMP2 and MMP9, we investigated the expression of MMP3, MMP11, MMP13 and MMP14 in tumour cells." (PMID 26284589, 2015). "Moreover, our findings expand our current understanding of how MMP3 is regulated, as well as how IRF8 functions in tumor biology." (PMID 26008967, 2015). "MMP-3/stromelysin-1 is highly expressed in the cancer microenvironment because MMP-3 is expressed by fibroblasts, endothelial cells and immune cells surrounding the tumor and cancer cells." (PMID 24531055, 2014). "As collagen is mainly deposited by during fibrosis, the overexpression of both alpha smooth muscle actin (ASMA), and matrix metalloproteinase 3 (MMP3) genes, two activated stellate cells (HSC) markers was noted in tumor cells extract compared to wild type cells." (PMID 25203629, 2014). "The most likely explanation is that MMP3 is required in the primary tumor, but no more needed once macroscopic metastases are established in the liver." (PMID 24023955, 2013). "Interestingly, our novel findings concerning expression levels of CXCL9, IL8, MMP1, MMP3 and COL1A1 are the converse of previously reported results: CXCL9 protein can modulate host cell infiltration and tumor behavior." (PMID 23405235, 2013). "We have confirmed over-expression of MMP3, UBE2C and p16 in tumours, by IHC." (PMID 21338529, 2011). "LCM-based analysis showed the 45 kDA band to be present in both the stromal and epithelial components of the tumor microenvironment, and that MMP-3 and MMP-10 mRNA levels were higher in tumors than paired normal tissues for each compartment." (PMID 20920372, 2010). "Immunostaining of MMP-3 showed a slight staining of the tumor cell's cytoplasm with no staining of the surrounding stromal and immune cells." (PMID 19531263, 2009). "In contrast, tumour cells secreted abundant MMP-3 and MMP-9 following TNF treatment, suggesting the use of nonredundant pathways by IL-17 and TNF." (PMID 19014637, 2008). "In contrast, normal fibroblasts showed no variation in IPC in relation to MMP genotype, with MMP-3 5A/5A fibroblasts exhibiting significantly lower levels of IPC than their tumor-derived counterparts (p = 0.04)." (PMID 17922906, 2007). "When fibroblast IPC was related to MMP SNP genotype, we identified a significant association between the high-expressing MMP-3 5A/5A genotype and high IPC of donor fibroblasts for the tumor-derived populations, though not in the normal fibroblast donors." (PMID 17922906, 2007). "This showed that the MDA MB 468 tumor cells used in the invasion assays in this study do not express MMP-1 or MMP-3, even following culture with fibroblast CM, whereas the fibroblast populations express both of these MMPs." (PMID 17922906, 2007).
tumor (continued). "Their studies revealed further elevated MMP2, MMP3, and TIMP2 concentrations from patients after tumour resection, which might function as a predictive value for early detection of tumour recurrence." (PMID 16901349, 2006). "In the Hs578T xenograft stroma, MMP-1 was absent while MMP-3 was observed at a higher level in the stroma as compared to the tumour cells." (PMID 16430785, 2006). "They showed a correlation for MMP1 expression and tumour aggressiveness, but no detectable expression for MMP3." (PMID 16901349, 2006). "Besides overexpression of MMP7, a known β-catenin-dependent target gene in colon cancer, the results show an overexpression of MMP1, MMP3, MMP11, MMP12 and MMP13 in desmoid tumours compared to normal fibroblasts (fascia tissue)." (PMID 15054469, 2004). "However, when combined with cisplatin, the synergistic effect led to a significant reduction in tumor growth, indicating that MMP3 inhibition enhances cisplatin sensitivity rather than acting as a standalone treatment." (PMID 40362252, 2025). "These interactions may explain why the knockdown of MMP3 with siRNA alone did not significantly reduce tumor growth in our study." (PMID 40362252, 2025). "It decreases the tumorigenesis marker such as matrix metallopeptidase 3 (MMP-3), interleukin-6 (IL-6), tumor necrosis factor-α (TNF-α), and proliferating cell nuclear antigen (PCNS), and stem cell markers including CD133 leading to reducing tumor size of REM134 canine mammary carcinoma." (PMID 38188673, 2023). "MMP3 and MMP12 are both archetypal matrix metalloproteinases (MMPs), a group of protein hydrolases containing active Zn2+ that are involved in many functions related to self-stabilization, such as tissue repair and immune and pathological processes, including tumor, fibrosis, and infection." (PMID 37503314, 2023). "Furthermore, a protein–protein interaction analysis obtained from the STRING website showed a direct interaction between SPP1 and CD44, MMP3, MMP7, TIMP1 and fibronectin-1, all of which are directly involved in the extracellular matrix remodeling and promotion of tumor metastasis." (PMID 38067407, 2023). "MMP-3 and MMP-7 expression in tumor cells may contribute to an apoptosis resistant phenotype." (PMID 36776395, 2022). "Thus, the LuM1-derived oncosomes could contain MMP3 and CD326/EpCAM, whose transfer may induce stemness in recipient cells in the local tumor microenvironment and distant organs." (PMID 32260433, 2020). "Oncosomal MMP3 also plays transcriptional roles in the induction of the cell communication network factor CCN2/CTGF, a finding which may be important for understanding a mechanism of tumor–stroma progression and metastasis." (PMID 32260433, 2020). "MMPs as a family of zinc-dependent proteolytic enzymes include MMP-1, MMP-3, and MMP-9, have the ability to degrade collagen and other ECM proteins, and play a crucial role in different pathophysiology conditions, such as invasion, vascular remodeling, angiogenesis, and tumor metastasis." (PMID 31762729, 2019). "It is tempting to speculate that, in a scenario where most adhesion and gap junction molecules are already downregulated, upregulation of MMP3 is not a sine qua non step towards tumor cell invasion and metastasis." (PMID 30323202, 2018). "Both tumor foci in the lungs and weights of the lungs from mice that received MMP3KD 3T3-A-EXO-treated 3LL cell transfer were reduced compared with mice that received NC 3T3-A-EXO-treated 3LL cell transfer, suggesting that MMP3 promoted 3T3-A-EXO-mediated 3LL tumor cell metastasis in vivo." (PMID 29137230, 2017). "Furthermore, MMP3 is SIRT1-dependently secreted from fibroblasts and facilitates tumor growth." (PMID 26992208, 2016). "Thus, MMP-3 might promote spontaneous metastasis in 4T1.2 and EO771.LMB tumours in part via proteolytic processing of PTHLH and MMP-9." (PMID 25633981, 2015).